GFAP (glial fibrillary acidic protein)
Diseases named in the same sentence as GFAP in open-access papers (continued):
Sharing a sentence is not in itself a finding about the gene and the disease.
COVID-19 (continued). "GFAP levels were increased in neuro-COVID-19 and long COVID-19 patients compared to non-neuro-COVID19 or non-long-COVID-19 patients, respectively." (PMID 41516418, 2026). "GFAP and NFL are markers of neuroinflammation that rise with age, increase in a severity-dependent manner during COVID-19 infection, and are elevated in people with persistent neurological complications of COVID-19." (PMID 41369364, 2025). "In COVID-19-associated ON, all serum samples were negative for AQP4 and GFAP antibodies, four (33.3%) patients were MOG-IgG-positive (titres were 1:100 in three patients and 1:32 in one patient), and one patient was CRMP5-IgG-positive (titre, 1:10)." (PMID 40728559, 2025). "Notably, in hospitalized COVID-19 patients with neurological complications, NFL and GFAP levels were higher complications or healthy controls." (PMID 40563736, 2025). "GFAP immunostaining revealed different astrocytic morphologies between cases with and without COVID-19." (PMID 38801558, 2024). "AD patients with COVID-19 also presented with extensive hippocampal astrocyte dysregulation as compared to their Non-COVID counterparts exhibited by our quantifications of GFAP and ALDH1L1." (PMID 39154174, 2024). "The objective of this work was to investigate the relationship among nervous system biomarkers (NfL, TAU, GFAP, and UCH-L1), biochemical parameters, and viral loads with heterogeneous outcomes in a cohort of severe COVID-19 patients admitted in Intensive Care Unit (ICU) of a university hospital." (PMID 37996731, 2024). "AD and DS-AD COVID-19 negative (COVID-) cases exhibited an increase in the density of GFAP labeled cells, with shorter, stubbier processes indicative of an inflammatory glial-induced response to the AD pathology (Fig. 4a5, b5, b8)." (PMID 38801558, 2024). "With regard to COVID-19, several studies showed an increase of CSF and blood NfL and GFAP in moderate and severe cases of acute disease, even without major central-nervous pathologies." (PMID 38438479, 2024). "The concentrations of NfL and GFAP were found to be elevated in 405 non-hospitalized COVID-19 patients, with plasma GFAP levels observed to be significantly two-fold higher in critically ill patients with COVID-19 when compared to healthy controls." (PMID 37958721, 2023). "Plasma NfL and GFAP was also assessed in hospitalized and non-hospitalized COVID-19 patients with neuro-PASC." (PMID 37545721, 2023). "Levels of NfL and GFAP were also found increased in mild-to-moderate COVID-19 without evidence of neurological symptoms." (PMID 37545721, 2023). "Although sex differences were found in our small population, it does not appear that young healthy persons with mild COVID-19 symptoms experience changes in the brain injury biomarkers NfL, GFAP, tau, or UCHL1." (PMID 37284701, 2023). "Neurofilament light chain (NfL), glial fibrillary acidic protein (GFAP), and total-tau protein (tau) are novel blood biomarkers of neurological injury, and may be used to predict outcomes in critical COVID-19." (PMID 37768470, 2023). "Finally, an investigation of neuronal (NfL) and astrocyte damage (GFAP), myeloid activation (sCD163) and BBB permeability (MMP-9 and TIMP-1) was performed on the CSF samples of hospitalized COVID-19 patients with severe NS on hospital admission." (PMID 37759493, 2023). "Two studies were included in the meta-analysis that compared the levels of GFAP between COVID-19 survivor and non-survivor groups." (PMID 37958721, 2023). "Both the increase of TSPO in blood vessels and perivascular GFAP could point to disruption of the BBB following SARS-CoV-2 infection, also witnessed in COVID-19 patients." (PMID 37516868, 2023). "GFAP (r = 0.585; p < 0.001), NfL (r = 0.637; p < 0.001) and T-tau (r = 0.403; p = 0.007) were significantly correlated with age for patients with COVID-19, but not in controls." (PMID 36769057, 2023). "GFAP and tau were also predictors of one-year mortality in critical COVID-19, albeit not independent predictors." (PMID 37768470, 2023).
COVID-19 (continued). "We observed a significant difference in the pooled GFAP levels between survivor and non-survivor groups of COVID-19 patients." (PMID 37958721, 2023). "When compared to the same healthy controls (n = 60), across all timepoints, both COVID-19 subgroups (COVID and neuro-COVID) showed increased levels of NfL, GFAP, and tTau (but not UCH-L1)." (PMID 38135686, 2023). "Based on our data, it appears that mild COVID-19 in young adults does not increase plasma NfL, GFAP, tau, or UCHL1." (PMID 37284701, 2023). "NfL, GFAP, and tau on ICU admission for critical COVID-19 are predictors of one-year mortality." (PMID 37768470, 2023). "Patients with COVID-19 without substantial neurological symptoms had significantly higher plasma concentrations of GFAP, a marker of astrocytic activation/injury, and of NfL and T-tau, markers of axonal damage and neuronal degeneration, compared with controls." (PMID 36769057, 2023). "In the present study, no dynamic of GFAP or UCH-L1 serum concentrations was observed throughout the ICU stay of patients with severe form of COVID-19, p = 0.549 and p = 0.425, respectively." (PMID 36363686, 2022). "COVID-19 patients who did not survive the infection and those who developed COVID-encephalopathy had elevated levels of p-tau 181, along with NfL and GFAP." (PMID 36268187, 2022). "The authors demonstrated that GFAP but not UCH-L1 levels were higher in the COVID-19 subgroup even after an adjustment for age and sex." (PMID 36363686, 2022). "Whilst the absolute concentrations are not directly comparable with the COVID-19 cohort (as the samples were plasma rather than serum), GFAP and NfL were elevated in patients with severe disease to a similar magnitude as the COVID-19 cohort." (PMID 36065116, 2022). "Similarly, in a study of hospitalized patients with moderate to severe COVID-19, NFL and/or glial fibrillary acidic protein (GFAP), an astroglial injury/activation marker, were elevated [93•]." (PMID 34843065, 2021). "Immunofluorescence analysis revealed an increase in ACE2 (2.3 ± 1.3 vs. 1.0 ± 0.1; p < 0.0001) and Iba1 expression (3.06 ± 0.6 vs. 1.0 ± 0.1; p < 0.01) in COVID-19 sections whereas no changes in GFAP were observed." (PMID 34829775, 2021). "Furthermore, two other studies demonstrated that serum GFAP was elevated in COVID-19 patients with no neurological symptoms compared to controls and normalized over the time course of 2 months after recovery." (PMID 39451987, 2024). "Thus, the aim of this study was to investigate the relationship among nervous system biomarkers (NfL, TAU, GFAP, and UCH-L1), biochemical parameters, viral loads, and heterogeneous outcomes in a cohort of severe COVID-19 patients at admission in the ICU of a public hospital." (PMID 37996731, 2024). "Indeed, long COVID-19 subjects with post-acute neurological complications showed elevated serum GFAP during early (<90–120 days), but not late, recovery." (PMID 39451987, 2024). "However, in this study, we demonstrate significantly elevated plasma concentrations of GFAP, NfL and T-tau in patients with COVID-19, but with non-substantial neurological affectation, compared with controls." (PMID 36769057, 2023). "Clinically, patients with COVID-19 without substantial neurological symptoms showed significantly higher plasma concentrations of GFAP, a marker of astrocytic activation, and of NfL and total tau, markers of axonal damage and neuronal degeneration, compared with controls." (PMID 38104129, 2023). "Among the excluded studies, 15 did not report outcomes of interest (NfL and GFAP) in both COVID-19 and healthy controls, six did not include healthy controls, three were reviews, and two were editorial reports; note that a few reports belonged to more than one category." (PMID 37958721, 2023).
COVID-19 (continued). "Therefore, the purpose of our study was to investigate whether neurofilament light (NfL), glial fibrillary acidic protein (GFAP), tau, or ubiquitin carboxyl-terminal esterase L1 (UCHL1) are elevated in the plasma of young adults with mild COVID-19 symptoms." (PMID 37284701, 2023). "Twelve participants diagnosed with COVID-19 had plasma collected 1, 2, 3, and 4 months after diagnosis to determine whether NfL, GFAP, tau, and UCHL1 concentrations increased over time or whether plasma concentrations were elevated compared with COVID-19-naïve participants." (PMID 37284701, 2023). "GFAP and NfL levels were significantly higher in COVID-19 non-survivors than in COVID-19 survivors." (PMID 37958721, 2023). "However, among severe COVID-19 patients, the high plasma levels of NfL and GFAP in patients without severe NS suggest the presence of subclinical central nervous system involvement." (PMID 37759493, 2023). "Notably, there were very few proliferating (1.9% of all GFAP+) reactive astrocytes in COVID-19 specimens with no obvious signs of edema." (PMID 38066208, 2023). "In addition, the same study also showed that GFAP is higher in a severe form rather than in a moderate form of COVID-19, and demonstrated a positive correlation between GFAP and age." (PMID 36363686, 2022). "Interestingly, GFAP staining intensity was not increased in the perivascular compartment in COVID-19 patients in our study." (PMID 35785352, 2022). "However, a recent study observed an increase in GFAP immunoreactivity near the ONH regions in some cases of COVID-19 patients, but not near the middle retinal regions." (PMID 34829775, 2021). "Glial fibrillary acidic protein, a marker of astrocytic activation, was not elevated in the CSF or serum of any group, suggesting astrocytic activation is not a major mediator of neuronal damage in COVID-19." (PMID 34396099, 2021). "Evidence for the absence of elevated serum GFAP sampled at admission time in COVID-19 patients also exists, which might be attributable to the heterogeneity of disease severity among different COVID-19 patient cohorts." (PMID 39451987, 2024). "Herein, we determined whether the plasma levels of NfL and total tau (T-tau, another marker of axonal damage and neuronal degeneration), as well of GFAP, were altered in COVID-19 patients without major neurological manifestations, as compared with non-infected and neurologically healthy controls." (PMID 36769057, 2023). "At the convalescent time point, serum GFAP concentrations were no higher than controls irrespective of disease severity, but serum NfL concentrations persisted at levels that were higher in patients who had developed moderate and severe COVID-19 compared with controls." (PMID 36065116, 2022). "The levels of NFL, GFAP, and ubiquitin carboxy-terminal hydrolase L1 levels L1 (UCHL1) in hospitalized COVID-19 patients without a history of dementia were as high as in non-COVID AD controls." (PMID 40563736, 2025). "It is interesting that previous studies that investigated the same biomarkers presented slightly different results, reporting the significant difference in NfL, GFAP, and TAU levels between survivors and deceased severe COVID-19 patients, but they did not observe the same to UCH-L1 levels." (PMID 37996731, 2024).
multiple sclerosis (99 papers, 2010 to 2026). A progressive autoimmune disorder affecting the central nervous system resulting in demyelination. "IL8/CXCL8 has been implicated in multiple diseases such as multiple sclerosis, glial fibrillary acidic protein autoimmunity, and infectious or post‐infectious syndromes including SARS‐CoV‐2 infection." (PMID 40781580, 2025). "Preclinical data demonstrated an upregulation of either GFAP alone or the combination of GFAP and NfL in murine multiple sclerosis models, associated with active states of inflammation and the disease peak." (PMID 39831665, 2025). "Serum biomarkers as neurofilament light chain (sNfL) and glial fibrillary acidic protein (sGFAP) enabled early identification of multiple sclerosis (MS) patients at risk of relapse-associated worsening (RAW) or progression independent of relapses (PIRA)." (PMID 40852725, 2025). "In multiple sclerosis (MS) patients under therapy, the increase of serum glial fibrillary acidic protein (sGFAP) concentrations is associated with the course of 'progression in absence of relapse' (PIRA)." (PMID 41237262, 2025). "Neurofilament light(NfL) and glial fibrillary acidic protein(GFAP) are associated with disease activity in multiple sclerosis(MS), however use in monitoring remains limited." (PMID 40699373, 2025). "Fourth, we excluded diagnoses including neuromyelitis optica spectrum disorder (NMOSD), multiple sclerosis (MS), GFAP astrocytopathy, ADEM, central nervous system damage caused by neurosyphilis, and AIDS." (PMID 40766314, 2025). "We discovered 72 proteins associated with multiple sclerosis at a Bonferroni‐adjusted p value of 0.05, including established markers such as neurofilament light chain and glial fibrillary acidic protein." (PMID 38282238, 2024). "In both the multiple sclerosis subgroups, greater GFAP levels remained as the only significantly associated biomarker with more severe DTI measures." (PMID 37361716, 2023). "We further demonstrate a potential correlation between GFAP and age, which is exemplarily known for healthy participants as well as patients with Parkinson's disease and multiple sclerosis." (PMID 39831665, 2025). "In terms of prognostic significance, our findings align with previous studies that have demonstrated great utility of the combined assessment of NfL and GFAP correlating with disease activity and disability in multiple sclerosis." (PMID 39831665, 2025). "Elevated GFAP levels are also observed in various neurological conditions, including multiple sclerosis and cerebrovascular disease." (PMID 41163175, 2025). "Identified in multiple sclerosis brain tissue in 1969, GFAP quickly became a key astrocyte marker and has since been widely used for selectively targeting astrocyte expression in mice via the GFAP promoter." (PMID 40346659, 2025). "Elevated IL-6 levels in the CSF were found in individuals with progressive MS, and CSF IL-6 showed positive correlations with the Expanded Disability Status Scale, the Multiple Sclerosis Severity Score, and CSF glial fibrillary acidic protein levels." (PMID 40175894, 2025). "Background and Aims: GFAP is an astrocytic biomarker that is upregulated in various neurological conditions, including multiple sclerosis (MS)." (PMID 40542572, 2025). "There is debate on the role of glial fibrillary acidic protein (GFAP) as a reliable biomarker in multiple sclerosis (MS) and neuromyelitis optica spectrum disorder (NMOSD), and its potential to reflect disease progression." (PMID 39064479, 2024). "GFAP in turn has been suggested as a marker for multiple sclerosis and traumatic brain injury but based on our results does not respond to peripheral nervous system demyelination." (PMID 37606798, 2023). "Plasma GFAP is also increased in neuroinflammatory conditions, including multiple sclerosis, and is a top biomarker candidate for the progressive form of the disease." (PMID 36607770, 2023).
multiple sclerosis (continued). "In multiple sclerosis patients, the immuno-modulating treatment daclizumab resulted in secondary GFAP autoimmunity." (PMID 35903170, 2022). "Taking the cytoskeleton as an example, glial fibrillary acidic protein (GFAP) is the protein most vulnerable to oxidative damage in multiple sclerosis, Pick's disease, and aging." (PMID 33902446, 2021). "Neuromyelitis optica (NMO), multiple sclerosis (MS) and autoimmune glial fibrillary acidic protein (GFAP) astrocytopathy are idiopathic inflammatory demyelinating diseases (IIDDs) that mainly present as encephalomyelitis." (PMID 34367165, 2021). "Protein up-regulation of GFAP was also found in other neurological diseases such as multiple sclerosis, SLE, or epilepsy, indicating a link between immunological processes and neurological diseases." (PMID 34943212, 2021). "Astrocytes are activated in response to CNS injury and diseases like multiple sclerosis (MS) and undergo astrogliosis characterized by increases in proliferation, hypertrophy, and glial fibrillary acidic protein (GFAP) expression." (PMID 28577576, 2017). "Our findings also identified GFAP positive exosomes in the peripheral circulation of mice and increased levels of circulating exosomes in the mouse model of multiple sclerosis, EAE." (PMID 28663721, 2017). "For instance, in progressive forms of multiple sclerosis, blood NfL levels may remain normal despite clinical deterioration, while GFAP levels better reflect disease progression." (PMID 40507935, 2025). "Nfe2l2 upregulation was similar between astrocytes from GFAP-Nrf2 mice (fold change 2.3 versus wildtype control) and multiple sclerosis astrocytes (fold change 1.8 versus healthy control) (IPA Analysis Match19,29), indicating a disease-relevant modulation of astrocytic Nrf2 activation in the mice." (PMID 37291151, 2023). "Indeed, the use of plasma NfL and GFAP levels in patients at different landmarks of multiple sclerosis (NeurofilMS) is currently being studied in a clinical trial." (PMID 34682919, 2021). "GFAP, an acidic protein belonging to the family of intermediate silk proteins, is the cytoskeleton protein of specific astrocytes, which was first separated from the white matter plaque of multiple sclerosis patients." (PMID 30285781, 2018). "Multiple sclerosis patients have increased CSF GFAP levels when compared to controls." (PMID 28444098, 2017). "Multiple sclerosis patients with worse ambulation or more severe disability have higher CSF GFAP levels than less disabled patients and controls, suggesting that CSF GFAP may be a biomarker of clinical progression and prognosis." (PMID 28444098, 2017). "The presence of citrullinated GFAP has also been observed in multiple sclerosis, hepatic fibrosis, and other neuroinflammatory disorders, raising questions about whether citrullination is a general marker of neuroinflammation or plays a unique role in AD progression." (PMID 40690136, 2025). "Elevated peripheral GFAP and NfL levels can also be observed in other conditions, including traumatic brain disorders, neurodegenerative disorders (e.g., Parkinson disease and amyotrophic lateral sclerosis), and autoimmune disorders of the CNS (e.g., multiple sclerosis)." (PMID 38735950, 2024). "Based on our experience of the clinical and research utility of blood NfL in multiple sclerosis, NfL and/or GFAP may be used for allocation of rehabilitative resources, and selection of participants for clinical trials of neuro‐restorative therapies, and monitoring the response to such therapies." (PMID 38805359, 2024). "In the murine model of multiple sclerosis, we found that MP intranasally administered was able to reduce the inflammatory cytokines as well as the expression of activation markers of glia and astrocytes (Iba1 and GFAP, respectively) and improved the clinical score." (PMID 35745768, 2022).